SERPINB9P1 (serpin family B member 9 pseudogene 1)
Synonyms: MGC39372
Gene: Long non-coding RNA gene on chromosome 6 (2,851,230 to 2,886,183, reverse strand). Ensembl gene ENSG00000230438.
Diseases named in the same sentence as SERPINB9P1 in open-access papers:
SERPINB9P1 is named in the same sentence as 3 diseases in open-access papers, as found by Europe PMC text mining. Sharing a sentence is not in itself a finding about the gene and the disease.
SERPINB9P1 shares sentences with these, for which no sentence is quoted: asthma (1 paper); childhood asthma (1); leishmaniasis (1).